CD36 (CD36 molecule (CD36 blood group))
Diseases named in the same sentence as CD36 in open-access papers (continued):
Sharing a sentence is not in itself a finding about the gene and the disease.
cancer (continued). "The correlation between CD36 expression and the four methyltransferases was also significant in multiple cancers, but also with a cancer type-specific pattern." (PMID 34234847, 2021). "Significant progress has been made in demonstrating regulatory networks that control the unique physiological characteristics of CD36, indicating that targeting CD36 is a potential cancer treatment strategy 8-11." (PMID 34234847, 2021). "In cancer, CD36 plays important roles in lipid homeostasis, immune response, angiogenesis, adhesion and metastasis." (PMID 34484199, 2021). "Because CD36 also plays a role in angiogenesis and inflammation, alterations in these processes in the endothelial KO and their potential effect on cancer progression cannot be excluded." (PMID 34314388, 2021). "Our data revealed that the majority of mouse and human cancer cell lines lack CD36 glycosylation, a modification enabling cell membrane localization, aside from expressing relatively little CD36." (PMID 34314388, 2021). "Another study showed that adipocytes induced CD36 expression in ovarian cancer cells, which promoted metastasis of cancer cells in peritoneum and omentum." (PMID 33401771, 2021). "To further illustrate the prognostic potential of CD36 in different cancers, we divided patients into high and low expression groups according to the median expression." (PMID 34234847, 2021). "In this study, we performed a pan-cancer analysis to elucidate the potential role of CD36 in cancers by investigating its prognostic value and current predictors for the efficacy of ICIs in multiple cancer types." (PMID 34234847, 2021). "CD36 plays a critical role in cancer progression, including cancer proliferation and metastasis, and it is also associated with poor survival of cancer patients." (PMID 34348794, 2021). "CD36 expression was significantly correlated with the 6 immune infiltrates in most of the cancer types, with COAD, KIRP, and LUAD displaying the best correlation." (PMID 34234847, 2021). "We showed that dynamic cysteine S-acylation of CD36 in adipocytes, endothelial cells, and cancer cells mediated intercellular LCFA transport." (PMID 34314388, 2021). "CD36 is an important lipid transporter that plays a critical role in cancer cell growth and metastasis via transport of lipid into cells, and by inhibition of CD36 that can significantly reduce metastatic activity." (PMID 34766135, 2021). "When inhibiting the function of CD36, the endogenously synthesized, unmetabolized lipids accumulate continuously in cancer cells, finally leads to metastatic lipotoxicity and cell death." (PMID 35003369, 2021). "In conclusion, we report that oxLDL seems to induce an increase in CD36 expression on HNC cell lines, enhancing the uptake of these lipids in cells to finally decrease cancer cell migration via the CD36/β-catenin pathway." (PMID 34063116, 2021). "The blockage of CD36 can effectively inhibit the stemness of CSCs and inhibit the progression of cancers in several studies." (PMID 34603046, 2021). "The multifaceted roles of CD36 in linking lipid metabolism and cancer progression are yet to be further investigated." (PMID 34314388, 2021). "We performed a pan-cancer analysis to elucidate the potential role of CD36 in cancer by investigating its prognostic value and current predictors for the efficacy of immune checkpoint inhibitors (ICIs) in multiple cancer types." (PMID 34234847, 2021). "For the fatty acid metabolism, leptin has been shown to upregulate CD36, a scavenger receptor functioning as a transporter of long‐chain fatty acids, in various normal and cancer cells, which in turn facilitates uptake of exogenous fatty acids." (PMID 33226729, 2021).
cancer (continued). "Knockdown either APOC2 or CD36 inhibited the malignant phenotype of cancer cells, and delayed GC PM progression in murine GC models." (PMID 34459127, 2021). "Among all the significant associations, CD36 expression was positively correlated with CD27, CD28, CD40, and ICOS in multiple cancer types, but negatively associated with CD40 in TGCA." (PMID 34234847, 2021). "The relationship between miR-21 and CD36, a lipid and fatty acid receptor, has been studied in multiple cancer types." (PMID 33916349, 2021). "There are several other examples for the ectopic expression of immune cell genes in cancer, such as CD36, CD70, CD40, CD47, CD172 and IDO1." (PMID 34885093, 2021). "With the recognition of the relevance of fatty acid metabolism in cancer, the implication of CD36 in the initiation, and progression of the tumorigenic process has been highlighted." (PMID 33050166, 2020). "Altogether these data indicate that chronic acidosis induces LD formation in cancer cells, with CD36 and DGAT1 as key players to mediate LD biogenesis through the uptake of exogenous FA and triglyceride synthesis, respectively." (PMID 31974393, 2020). "The presence of CD36+ metastasis initiating cells also correlated with poor prognosis in a number of cancer types and anti-CD36 neutralizing antibodies induced regression of the lymph node and lung metastasis in murine models." (PMID 33339340, 2020). "CD36 enhances FA uptake and FA oxidation, and plays a critical role in cancer cell growth and metastasis." (PMID 32850342, 2020). "The lipogenic pathway is also an important hall marker of HCC that also resulted from the activation of the AKT pathway, and cd36 has also been reported to increase in cancer." (PMID 32102330, 2020). "In response to antiangiogenic drugs, cancer cells display a significant increase in external FA uptake and transportation through the upregulation of FA transporters (CD36, FABP, SLC27) as well as an augmentation of mitochondrial CPT1-mediated FAO." (PMID 33339398, 2020). "In the presence of CAAs some cancer cells can acquire exogenous free fatty acids (FFAs) released by CAAs through the cell surface fatty acid translocase CD36 and switch their metabolic program from glycolysis to FAO." (PMID 32211323, 2020). "Evidence indicates that the lipid scavenger receptor CD36 has pro-metastatic functions in several cancers." (PMID 33232276, 2020). "In cancer studies, CD36 is investigated mostly in relationship with thrombospondins (TSPs) and, to a lesser extent, with transforming growth factor-β (TGF-ß)." (PMID 32781778, 2020). "In contrast, CD36, another cancer-activating lipid transporter, is undetectable in Bo1 cells regardless of culture conditions." (PMID 32879136, 2020). "Coculture of cancer cells with adipocytes results in upregulation of the CD36 expression, leading to increased FA uptake by cancer cells." (PMID 33339398, 2020). "CD36 molecule was examined during several diseases, including cancer, where it seems to support development of metastasis." (PMID 32781778, 2020). "CD36 can be expressed on several different cell types, including both lymphocytes, cancer cells, and fibroblasts." (PMID 33352957, 2020). "The effect of CD36 on the migration and invasion of cancer cells is due to the downregulation of E-cadherin and β-catenin." (PMID 32380783, 2020). "CD36 contributes to the progression and metastatic potential of cancer by several mechanisms, such as activation of cancer stem cells, epithelial-to-mesenchymal transition, and chemoresistance." (PMID 32781778, 2020). "There are studies have demonstrated the important role of fatty acid uptake and CD36 in cancer progress." (PMID 32327627, 2020). "Our findings support recent studies demonstrating that cancer cells expressing high levels of the FA receptor CD36 show high metastatic potential." (PMID 32139877, 2020).
cancer (continued). "While CD36 (also known as platelet glycoprotein 4) is a multifunctional protein that regulates angiogenesis and cellular adhesion in addition to FA uptake, CD36 as a FA transporter has emerged as an important player in the progression of many cancer types." (PMID 32226926, 2020). "In particular, CD36 has been demonstrated to be crucial for metastatic dissemination of cancer cell in different tumor type, with its high expression being correlated with poor prognosis." (PMID 32486505, 2020). "In contrast, we found that the level of CD36 mRNA is significantly lower in cancer tissues as compared to normal tissues." (PMID 32850342, 2020). "Using bioinformatics analyses, we ascertained that CD36 expression was increased in metastatic GC specimens in The Cancer Genome Atlas and Gene Expression Omnibus databases and correlated with poor prognosis." (PMID 33232276, 2020). "We have also showed that CD36 regulates survivin, a member of the inhibitor of apoptosis (IAP) family that is highly expressed in most cancer and associated with a poor prognosis." (PMID 32850342, 2020). "Recently, a high-fat diet was shown to specifically promote the metastatic potential of specific cancer cells in a CD36-dependent manner." (PMID 31410220, 2019). "An increasing number of studies have found that CD36 plays a vital role in the development of cancers, especially as it relates to the process of cancer metastasis." (PMID 31655604, 2019). "Notable advances have been made in demonstrating the regulatory networks that govern distinct physiological properties of CD36, and this has identified targeting CD36 as a potential strategy for cancer treatment." (PMID 31410189, 2019). "Adipocyte conditioned medium induces the expression of CD36, an integral membrane fatty acid receptor which subsequently promotes the uptake of fatty acids by cancer cells." (PMID 31847105, 2019). "SR-BI was highly expressed in TAM and CAF versus 4T1 cancer cells, and CD36 was exceedingly expressed in TAM over CAF and 4T1 cells (p < 0.01)." (PMID 31346166, 2019). "Correlated with invasion of tumors and metastasis, CD36 has been extensively proposed as a prognostic biomarker for various types of cancers, mostly of epithelial origin." (PMID 31022903, 2019). "CD36-induced metastasis potential has been reported to be based on the lipid metabolism of cancer cells." (PMID 31410189, 2019). "CD36 can be upregulated in cancer cells by adipocytes and high-fat diet to increase fatty acid uptake and promote tumour growth and metastases." (PMID 31035848, 2019). "HRG released from platelets have been shown to promote angiogenesis in cancer by interfering with thrombospondin 1 and thrombospondin receptor CD36-mediated antiangiogenic signaling." (PMID 30944671, 2019). "CD36 is involved in cardiovascular and metabolic diseases, as well as immune responses and cancer metastasis." (PMID 31379931, 2019). "Recent studies have also shown that CD36 expression and fatty acid uptake in cancer cells can be increased by adipocytes and high-fat diet, resulting in significantly enhanced survival and metastases." (PMID 31035848, 2019). "Relationship between CD36 and ccRCC was rarely documented, while it is noteworthy that CD36 is estimated most expressed in many cancer patients." (PMID 31528216, 2019). "CD36 is a key regulator in angiogenesis and fatty acid metabolism and is a potential driver in metastatic cancer stem cells (CSCs)." (PMID 31739580, 2019). "Here, we provide an overview on the structure, regulation, ligands, functions, and clinical trials of CD36 in cancer." (PMID 31410189, 2019). "Deleting CD36 or using a blocking monoclonal antibody slowed cancer progression and disease severity." (PMID 31922096, 2019). "Taken together, these findings suggest that MICs and the cancer EMT process are both regulated by lipid metabolism through the CD36-dependent pathway." (PMID 31410189, 2019).
cancer (continued). "Accumulating evidence indicates that CD36 initiates metastasis and correlates with an unfavorable prognosis in cancers." (PMID 31655604, 2019). "Multiple studies have revealed that CD36-positive cancer cells initiated metastasis via heightened lipid metabolism." (PMID 31089396, 2019). "This review presents data to support CD36 as a potential prognostic biomarker in cancer, its current stage towards achieving bona fide biomarker status, and knowledge gaps that must be filled before further advancement towards clinical practice." (PMID 30069479, 2018). "Learning from paths travelled in understanding other receptors as cancer-related biomarkers, one can argue that there are still plenty of blank spots on the CD36 cancer-related map." (PMID 30069479, 2018). "One of the first mentions of CD36 as a possible biomarker for cancer prognostics dates more than 15 years, when it was included in a panel of immunophenotyping for high risk for acute myeloblastic leukaemia." (PMID 30069479, 2018). "In cancer studies, CD36 is investigated mostly in relationship with TSPs, a family of matrix proteins acting as ligands, and most data are related to TSP interactions and, to a lesser extent, TGFß." (PMID 30069479, 2018). "CD36 has been demonstrated to be involved in metastasis of various cancer types indicating its pro-tumorigenic properties." (PMID 30573731, 2018). "Recently, both CCLX and PDX models were used to assess the effect of blocking the fatty acid receptor CD36 on the metastasis of cancer which revealed CD36 as an anti-metastasis target." (PMID 28499452, 2017). "In a cancer scenario, the uptake of fatty acids—mediated by CD36—and their oxidation sustain cancer-initiating cells and promote metastasis." (PMID 29354634, 2017). "We found that elevated expression of fatty acid uptake genes, CAV1 and CD36, were consistently associated with a high EMT score across all cancers." (PMID 26725848, 2016). "Using gene expression profiles, we established a gene-signature (CAV1, CD36, MLXIPL, CPT1C, CYP2E1) that strongly associated with epithelial-mesenchymal program across multiple cancers." (PMID 26725848, 2016). "Alternatively, the use of SR-BI mutants and/or SR-BI/CD36 chimeric constructs should also allow us to better understand the role of SR-BI in cancer." (PMID 27774064, 2016). "Notably, advances have revealed the regulatory networks governing distinct physiological properties of CD36, thereby identifying targeting CD36 as a potential strategy for cancer treatment." (PMID 42164471, 2026). "Increasing evidence implicates CD36 in the progression of various cancers." (PMID 41595136, 2026). "These molecules are significantly correlated with CD36, and high expression of CD36 may increase β-oxidation and ROS production, which may contribute to the recurrence of dormant cancer cells." (PMID 41465497, 2025). "This metabolic signature is closely tied to both CD36 and cancer stem cells (CSCs)." (PMID 39984452, 2025). "Moreover, CD36, another transmembrane glycoprotein, facilitates the uptake of free FAs and cholesterol and plays essential roles in cancer biology, including antigen presentation, inflammation, and angiogenesis." (PMID 39969135, 2025). "In addition, FATPs, CD36, and FABPs are responsible for absorbing exogenous fatty acids and giving cancer cells metabolic flexibility." (PMID 40538442, 2025). "This underscores the potential of the TSP-1/CD36/vascular axis as a promising anti-cancer target." (PMID 40075313, 2025). "Additionally, the knockdown of CD36 resulted in a reduction in adipocyte‐mediated invasion and migration of cancer cells." (PMID 39969135, 2025). "An interesting observation in multi-transcript genes is worth noting; first, the highest number of transcripts per gene that correlated with a phenotype in a cancer type was 19, and was limited to the CD36 (19 out of 24 transcripts), ABI3BP (19/29), and TCF4 (19/93) genes." (PMID 41048343, 2025).
cancer (continued). "Molecular subtypes of cancers also exhibited a remarkable correlation with CD36." (PMID 41550652, 2025). "Therefore, patients who test positive for CD36 should be intimately monitored to identify early cancer spread and consider alternative treatments promptly." (PMID 40060230, 2025). "Multiple cancer types enclosed sufficient CD36 transcripts upregulation (ENST00000435819)." (PMID 41550652, 2025). "The role of CD36 in cancer development, progression and metastasis thus requires further study." (PMID 40563926, 2025). "Research should also explore the potential of combining exercise with drugs that target lipid metabolism, such as inhibitors of FASN, ACC, or CD36, to create synergistic effects that might further enhance cancer treatment." (PMID 40487761, 2025). "Both PS and CD36 are suggested as potential therapeutic targets for cancer treatment." (PMID 39752516, 2025). "However, some pathways illustrated cancer-type-specific patterns, which indicate heterogeneous nature of CD36 to oncogenic pathways." (PMID 41550652, 2025). "CD36 has already been established to enhance EMT in multiple cancers." (PMID 40060230, 2025). "It is well-established that a lipid-rich diet can promote cancer metastasis; CD36 could thus contribute to cancer progression by stimulating lipid uptake and FA β-oxidation in cellular energy metabolism." (PMID 40563926, 2025). "In the cancer cervix, CD36 enhances EMT via interconnections with the TGF pathway." (PMID 40060230, 2025). "Moreover, using RT–qPCR, we found in several CRISPRa conditions that the cancer cells had lower expression of both CD36, a fatty acid transporter on the cell membrane, and CPT1b, a key regulator of FAO in the mitochondria, further confirming decreased FAO." (PMID 39905264, 2025). "CD36, a transmembrane glycoprotein, serves vital functions in lipid homeostasis, angiogenesis, immune response, cellular adhesion, and metastasis across different cancers." (PMID 40075313, 2025). "In addition, CD36 has been demonstrated to be enriched in cancer stem cells and coexpressed with the cancer stem cell markers integrin α6 and CD133 to drive glioblastoma progression." (PMID 39774047, 2025). "However, additional research is needed to explore the significance of CD36 phosphorylation in cancer." (PMID 39551780, 2024). "Consequently, CD36 presents a promising drug target, and the development of novel CD36 inhibitors, especially in combination with immunotherapy, holds significant potential for advancing cancer treatment." (PMID 39402302, 2024). "The cell surface transporter, CD36, has been identified as a crucial FA importer for cancer cells." (PMID 39725994, 2024). "CD36 has been identified as a new promising therapeutic target for cancer, since it strengthens metastasis initiation potential of cancer cells and upon blocking its lipid uptake activity, with a CD36 specific antibody, the size of lymph node metastases is reduced by 80–90%29." (PMID 38643249, 2024). "Moreover, there is growing evidence that high expressions of CD36 in certain cancer cells promotes cancer progression and metastasis." (PMID 38276607, 2024). "CD36 (fatty acid translocase), coordinating myocardial lipid metabolism by modulating lipid signaling and promoting the metabolism of long-chain fatty acids on cardiomyocytes, is upregulated in models for advanced cancers." (PMID 38987722, 2024). "CD36 is also expressed by several immune cells and involved in immune responses and may be a potential target in cancer immunotherapy." (PMID 39273384, 2024). "Data acquired in preclinical models of various malignancies indicate that inhibiting CD36 may effectively halt metastatic spread and serve as a predictive biomarker in cancer." (PMID 39062552, 2024).